Y_RNA (Y RNA )
Gene: Miscellaneous RNA gene on chromosome X (106,426,568 to 106,426,669, forward strand). Ensembl gene ENSG00000202407.
Homologues: Orthologues: chimpanzee Y_RNA (100% identical), macaque Y_RNA (96% identical). Paralogues in human: Y_RNA (90% identical), RNY3 (89% identical), Y_RNA (89% identical), RNY3P1 (88% identical), Y_RNA (88% identical), Y_RNA (87% identical), Y_RNA (86% identical), RNY3P11 (85% identical), Y_RNA (85% identical), RNY3P5 (84% identical), Y_RNA (84% identical), RNY3P14 (83% identical), and 97 more.